CATSPERD (catsper channel auxiliary subunit delta)
Description:
Auxiliary component of the CatSper complex, a complex involved in sperm cell hyperactivation. Sperm cell hyperactivation is needed for sperm motility which is essential late in the preparation of sperm for fertilization. Required for CATSPER1 stability before intraflagellar transport and/or incorporation of the CatSper complex channel into the flagellar membrane.
Synonyms: TMEM146; MGC39581
Tractability: Antibody: its Gene Ontology location is reachable by antibodies, with high confidence; UniProt predicts a signal peptide or a membrane-spanning region.
Gene: Protein-coding gene on chromosome 19 (5,720,637 to 5,778,734, forward strand). Ensembl gene ENSG00000174898.
Subcellular location: Cell projection, cilium, flagellum membrane
Subcellular location (Human Protein Atlas): Mid piece
Pathways (Reactome):
Reproduction: Sperm Motility And Taxes
Gene Ontology:
Molecular function: protein binding
Biological process: flagellated sperm motility; sperm capacitation; spermatogenesis
Cellular component: CatSper complex; plasma membrane; sperm principal piece
Genetic constraint (gnomAD): Loss-of-function variants: 57 observed, 71.2 expected, observed/expected ratio (o/e) 0.8, 90% interval 0.65 to 1. The upper end of that interval is the gene's LOEUF score, 1, which puts it in group 4 of 6, group 1 being the genes least tolerant of losing a copy. Missense variants: 853 observed, 891 expected, observed/expected ratio (o/e) 0.96, 90% interval 0.9 to 1.01. Synonymous variants: 354 observed, 360.32 expected, observed/expected ratio (o/e) 0.98, 90% interval 0.9 to 1.07.
Homologues: Orthologues: chimpanzee CATSPERD (98% identical), pig CATSPERD (64% identical), mouse Catsperd (50% identical), rat Catsperd (47% identical).
Diseases named in the same sentence as CATSPERD in open-access papers:
CATSPERD is named in the same sentence as 5 diseases in open-access papers, as found by Europe PMC text mining. Sharing a sentence is not in itself a finding about the gene and the disease. The quoted sentences say what the papers report.
asthenozoospermia (1 paper, 2022). "Importantly, in the mouse, the invalidation of any of the four pore-forming α subunits gene, CatSper1–4, or the auxiliary CatSperδ subunit gene was shown to cause asthenozoospermia by abrogating Ca2+ influxes and hyperactivated motility." (PMID 35409285, 2022).
leukemia (1 paper, 2019). A malignant (clonal) hematologic disorder, involving hematopoietic stem cells and characterized by the presence of primitive or atypical myeloid or lymphoid cells in the bone marrow and the blood. "We also detected the genes CATSPERD, PRR22, RFX2, and MILT1, which have been shown to be associated with leukemia." (PMID 31013791, 2019).
oral squamous cell carcinomas (1 paper, 2022). "Our study describes the neoexpression (Juno) and suppression (catsperD, dysferlin, Fer1L5 and otoferlin) of selected genes in oral squamous cell carcinomas (OSCCs)." (PMID 35330493, 2022).
cancer (1 paper, 2022). A tumor composed of atypical neoplastic, often pleomorphic cells that invade other tissues. "For some genes (CatsperB, CatsperD, Dysferlin, Fer1L5, Juno), a limited number of published literature referring to cancer is known." (PMID 35330493, 2022). "Taken all this information together, CatsperD might be a suitable biomarker for identifying other types of cancer." (PMID 35330493, 2022). "CatsperD transcripts have been found primarily in nasal and airway epithelia and oocytes but not at all in cancer." (PMID 35330493, 2022).
tumor (1 paper, 2022). "As a result of this approach, particularly Juno as a real tumor marker but also four additional genes, namely CatsperD, Dysferlin, Fer1L5, and Otoferlin remain to be useful in characterizing oral malignancies." (PMID 35330493, 2022). "Since these genes are expressed under limited, exclusive conditions, i.e., only in male spermatozoa and testis, we consider Catsperβ and Catsperδ as promising target molecules for new reliable tumor biomarkers in OSCCs." (PMID 35330493, 2022).